RNU6-658P (RNA, U6 small nuclear 658, pseudogene)
Gene: Small nuclear RNA gene on chromosome 5 (74,725,099 to 74,725,204, reverse strand). Ensembl gene ENSG00000207336.
Homologues: Orthologues: chimpanzee U6 (100% identical), macaque U6 (89% identical), guinea pig U6 (86% identical), rabbit U6 (81% identical), pig U6 (79% identical), dog U6 (78% identical). Paralogues in human: RNU6-38P (93% identical), RNU6-25P (92% identical), RNU6-29P (92% identical), RNU6-33P (92% identical), RNU6-1 (92% identical), RNU6-1145P (92% identical), RNU6-2 (92% identical), RNU6-20P (92% identical), RNU6-39P (92% identical), RNU6-3P (92% identical), RNU6-48P (92% identical), RNU6-4P (92% identical), and 1289 more.